SOX2 (SRY-box transcription factor 2)
Diseases named in the same sentence as SOX2 in open-access papers (continued):
Sharing a sentence is not in itself a finding about the gene and the disease.
tumor (continued). "Indeed, depletion of various stemness markers such as cluster of differentiation 44 (CD44) in breast CSCs or octamer-binding transcription factor 4 (OCT4) and SRY-Box Transcription Factor 2 (SOX2) in colon CSCs, prevented tumor metastasis and tumor growth." (PMID 39981232, 2025). "In our experimental setup, surgery, radiotherapy as well as CRT did not significantly alter SOX2 expression on CD133+ CTCs in patients of both tumor entities." (PMID 40083005, 2025). "Recent work has shown that pluripotency transcription factors, including Oct-4 and Sox2, are present in non-stem tumour cells and normal meningeal cells, limiting the potential role of these factors as differentiators between stem and non-stem cells." (PMID 39316249, 2025). "To evaluate the stemness role in ITAC prognosis, we analyzed, for the first time, the expressions of the Yamanaka factors KLF4, c-MYC, SOX2, OCT4, and NANOG in a cohort of patients with ITAC and investigate their possible roles in influencing tumor properties and survival." (PMID 41463190, 2025). "Given that the GSC state is not a stable clonal subpopulation but rather a plastic state induced by the tumor microenvironment, we scored cells based on classic GSC markers (PROM1, SOX2, NES, OLIG2, BMI1, NANOG, POU5F1) and defined the top 2% of cancer cells with the highest stemness scores as GSCs." (PMID 41041071, 2025). "Mechanistically, collagen I enhances stemness (Sox2, Oct4, CD133) through Slug-dependent EMT and, via DDR1–CD44 signaling, disrupts Hippo pathway regulation to activate YAP, thereby reinforcing therapeutic resistance and tumor progression." (PMID 41149589, 2025). "Additionally, SOX2 synergises with the transcription factor OCT4 to maintain the tumourigenic capacity of cervical CSCs, driving tumour proliferation and recurrence." (PMID 40665579, 2025). "NKX2–1 functions as a tumor suppressor in LUSC, and its deletion may promote SOX2-driven transformation by inhibiting SOX2 targeted genes, thereby accelerating the development of LUSC." (PMID 40568576, 2025). "Despite this variability, Sox2 expression was not correlated with tumor size, invasiveness, proliferative activity, or hormone levels, suggesting limited prognostic value so far." (PMID 40643539, 2025). "Although direct correlation between plasma and matched tumor expression levels of SOX2, PIWI proteins, and MALAT1 was not assessed in this study, prior research supports their concordance in several cancers." (PMID 40674376, 2025). "Moreover, the expressions of cancer stemness markers, including CD133 as well as SOX2 and ALDH1, in mouse tumor tissues were elevated in response to chronic DEHP exposure in immunohistochemical (IHC) staining and Western blot analysis." (PMID 40959920, 2025). "We enriched the CSC population through sphere culture from A549 and H1299 tumor-bearing mice and verified the enrichment using western blotting and flow cytometry to detect stem cell transcription factors (NANOG, OCT4, SOX2) and CSC surface markers (CD44, CD133)." (PMID 40093893, 2025). "As opposite to cancer cells, CD90+ cells were positive for the tri-methyl-histone H3 and negative for the tumor cell marker SOX2." (PMID 40703808, 2025). "Finally, components in the tumor microenvironment, such as cancer‐associated fibroblasts and immune cells, could foster resistance by supporting cell survival and restoring stem cell‐like properties independent of SOX2." (PMID 39736115, 2025). "Moreover, tumor cells were reprogrammed to express various stem cell markers (e.g. ALDH1A1, CD44, CD133, and SOX2), which are involved in self-renewal, stemness acquisition, and CRPC transformation." (PMID 39711287, 2025). "In addition, we performed immunohistochemistry experiments on BC tissues at different stages and found that with the progression of BC, the expression levels of tumor stemness-related markers (CD44, OCT4, SOX2, NANOG) gradually increased." (PMID 41387479, 2025).
tumor (continued). "SOX2’s activation by TGLI1 underscores its dual role in initiating cancerous traits and adapting to new metastatic niches, enabling CSCs to interact with and reshape their microenvironment to support tumor progression." (PMID 40016470, 2025). "Moreover, P. gingivalis-enhanced expression of SOX2, BMI1, and NANOG in tumor tissues were remarkably reduced by SCD1 knockdown." (PMID 40016182, 2025). "To assess whether PD-1 blockade alters tumor cell or TAM transcriptional profiles, we performed spatially resolved analysis of SOX2+ and IBA1+ compartments." (PMID 40960500, 2025). "Furthermore, cell lines obtained from such metastases retained the expression of some stemness factors (e.g., SOX2, KLF4, c-MYC) and were able to form tumorspheres in vitro, confirming the tumor stem cell behavior of these isolated subpopulations." (PMID 40806546, 2025). "To confirm whether GSC stemness is involved in the impaired tumor progression upon GPNMB depletion in macrophages and microglia, we performed immunofluorescence staining for SOX2 in shC and shGPNMB tumors." (PMID 40626360, 2025). "All tumor cells were SALL4+, a general GCT marker (SOX2 inlay)." (PMID 40025812, 2025). "SOX2 and NANOG, key transcription factors in cancer stem cell biology, may drive tumor progression and therapy resistance." (PMID 40227667, 2025). "Using biochemical experiments and GRN analysis, we propose SOX2 as an upstream regulator of NTRK2, targeting the PI3K pathway to control cell growth, while NTRK2 may play a pivotal role in tumor metastasis through interaction with E-cad." (PMID 40133476, 2025). "The key genes for CSCs to maintain stemness, such as OCT4, SOX2, and NANOG, were also significantly decreased after the combination treatment, further implying that the stemness of CSCs was reduced and different from that of normal tumor cells." (PMID 40785845, 2025). "We found that Sox2‐ and CD44‐positive GSCs remained present at unresected residual GBM tumor sites." (PMID 39721005, 2025). "It suppresses stemness traits of ESCC cells by targeting the deubiquitinating enzyme (USP8), diminishes the expression of stemness-related markers such as SOX2 and NANOG, decreases the sphere-forming capacity of drug-resistant cells, and lowers the incidence of tumor formation in vivo." (PMID 40710326, 2025). "In addition, IL-20RB overexpression upregulated the mRNA levels of several tumor stemness markers, including transcriptional factors such as NANOG, SOX2, and POU5F1, while IL-20RB knockdown downregulated their mRNA levels." (PMID 40806452, 2025). "In another study, mouse medulloblastoma cells expressing Sox2+, a genetic marker of chemoresistance, were found to ensheath capillaries, thereby creating a blood-tumour barrier (BTB) that reduces therapeutic agent access to the tumour." (PMID 40527011, 2025). "In the current treatment protocol, ΔNp63 showed significant downregulation in tumor tissue, while SOX2 showed no apparent inhibition." (PMID 40871074, 2025). "Conversely, reduced or absent SOX2 expression has been proposed as an independent marker of poor prognosis, reflecting a shift toward a less differentiated and more aggressive tumour biology." (PMID 41561279, 2025). "Although we found low SOX2 expression in ITAC with respect to non-malignant tissue, its high-level expression within tumor was associated with poor prognosis." (PMID 41463190, 2025). "Furthermore, Ki-67, TMEM33, and SOX2 protein expression in tumors from the sh-TMEM33 group exhibited a marked decrease, indicating a decrease in tumor aggressiveness and stemness." (PMID 40191724, 2025). "We performed IHC staining to investigate the expression of Sox2 and CD44 in tumor tissues." (PMID 39721005, 2025). "CAR also curbed HIF-1α and β-catenin tumor levels subsequently suppressing ALDH-1 and SOX2." (PMID 38962320, 2024).
tumor (continued). "In addition, HIF2α-specific targeted expression of known pluripotent factors, such as OCT4, SOX2, and NANOG, can affect stem cell function and promote tumor growth." (PMID 38243138, 2024). "Invitro, we found that CS at a specific concentration could increase thediameter and number of 786-O and ACHN tumor spheres, and the expression level ofRCSCs markers (CD44, Oct4, SOX2) was significantly increased." (PMID 38985013, 2024). "We also analyzed the expression of markers SOX2 and PDGFRA for all tumor types." (PMID 39609428, 2024). "In this study, for the first time, we found that Tregs enhanced the ‘stemness’ of HCC cells, demonstrated by increased TICs ratio, upregulated expression of TICs-related genes CD133, Oct3/4, Sox2, c-Myc, Klf4, Nanog, CD13, EpCAM, elevated tumor sphere formation, and tumorigenic ability." (PMID 39073490, 2024). "Moreover, costaining of the tumor cells for SOX2 and nestin demonstrated that mHsp70 was also abundantly expressed (as well as CD133) on the tumor stem cells positive for these markers." (PMID 39015084, 2024). "Regarding SOX2, despite lacking of previous studies, SOX2 modulates several features of tumor metastasis such as EMT, migration, and invasion." (PMID 38532463, 2024). "Moreover,ΔNp63α overexpression of 786-O and ACHN tumor spheres significantly increasedthe protein expression levels of RCSCs markers CD44, Oct4, and SOX2 comparedwith the control group." (PMID 38985013, 2024). "Primary AAC between and control non-tumor intestinal tissue groups did not significantly vary in terms of SOX2 epithelial expression (P = 0.153)." (PMID 38532463, 2024). "Notably, the analysis of HAS3, ABCC5, SOX2 and CD133 tumor mRNA transcripts showed that Pa + 4Mu combination therapy significantly downregulated gene expression, as was observed in the previous in vitro assays (p < 0.01)." (PMID 39039104, 2024). "Considering KMT2D’s role in the PI3K/AKT/SOX2 axis in NSCLC, which affects tumor growth, combined targeted therapy of KMT2D and PI3K may offer new treatment possibilities for LSCC." (PMID 39544292, 2024). "Within these tumors, cells with high N1-ICD expression were negative or low for SOX2, while SOX2-positive tumor cells were low for N1-ICD, which is in agreement with the model of reciprocal inhibition we identified." (PMID 39478150, 2024). "The transient GSI-mediated tumor growth control of HCC1599 xenografts cannot be explained by derepressed SOX2 expression as they are largely SOX2 negative." (PMID 39478150, 2024). "Analysis of tumor‐bearing brains revealed that targeting TAGLN expression in GSCs reduced the expression levels of TAGLN, the proliferation marker Ki67, and the GSC marker SOX2, but increased levels of the GFAP differentiation marker and Cleaved Caspase3." (PMID 38087889, 2024). "In cases where only Sox2 and Oct4 are used for reprogramming, no tumor formation was reported during extended monitoring periods." (PMID 38391956, 2024). "Moreover, MB157, MB57R and HCC1806 showed tumor cells co-expressing N1-ICD and SOX2 (17%, 13%, and 17%, respectively)." (PMID 39478150, 2024). "The enforced expression of Cirbp alone had little impact on the expression of stem cell-related markers (i.e., Nanog and Bmi-1) or slightly upregulated the expression of Sox2, Oct4 and ABCG2 in whole xenograft tumor lysates from CNE2 cells, as compared to those of control group (i.e., LV-con group)." (PMID 38419081, 2024). "The analysis of RRAS2 expression in non-tumoral mammary gland tissue of Rosa26-RRAS2fl/fl x Sox2-Cre mice shows a mean 3.2-fold above the expression of the murine Rras2 gene in non-tumor developing control breeders." (PMID 38987766, 2024). "In addition, SIX4, STAT3, IL-6, SOX2, and C-JUN were upregulated in tumor spheres compared to adherent cells." (PMID 39309424, 2024).
tumor (continued). "IHC staining of these xenograft tumours for previous stem cell-like markers, compared to the control xenograft tumours, showed that the percentage of CD44, NANOG, SOX9, SOX2 positive cells was reduced in the STC1-silenced group, and STC1 shRNA and circUBA2 co-transfection played a reversal role." (PMID 39103836, 2024). "SOX2 protein expression was found exclusively in the tumor cell nuclei, whereas SOX9 was expressed not only in the tumor cells but also in some parts of the tumor stroma." (PMID 38275880, 2024). "Regarding tumor formation, two studies conducted follow-ups for up to 50 weeks after Sox2 injection but neither observed tumor formation." (PMID 38391956, 2024). "Additionally, PepO treatment also resulted in a decrease in the tumor stem cell-related proteins ABCG2, OCT4, SOX2 and Olig2." (PMID 37925462, 2023). "Knowing that the pluripotency in differentiated cells could only be induced by a combination of three transcription factors, the team hypothesized that SOX2 and OCT4 must be activated in tumor stem cells." (PMID 37371030, 2023). "The main finding of our study is that the close margin, defined as tumor-free by the conventional histopathological examination, may show high levels of SOX2, CD44, and CXCR4 to an extent comparable to that observed in the relative tumor core." (PMID 38096163, 2023). "No significant reduction of the number of SOX2-positive stem-like cells due to the THz irradiation was observed in either the non-tumor or tumor cell cultures (p < 0.05), and no changes in the morphology cells were found, and no mature MAP2b+ appeared." (PMID 37047534, 2023). "Additionally, the presence of RNA, which encodes oncogenes or tumor suppressor genes that are characteristically expressed in HNSCC, like SOX2, CRYAB, and PTHLH, further suggests transmission of tumor RNA into platelets." (PMID 37455825, 2023). "In order to identify the most important cell type(s) leading to lower tumoral SOX2 levels in the CTH KO, a series of tumor microenvironment cell-specific CTH KO mice would have to be created (i.e knockout in endothelial cells, macrophages, astrocytes) which was beyond the scope of the current study." (PMID 37300955, 2023). "In that paper, we showed that Sox2 expression is a negative prognosticator of OS independently from tumor grade." (PMID 36836440, 2023). "The established organoids recapitulate several of the histological features of the tissue of origin (such as differently sized and shaped nuclei) and show a stem cell phenotype (with expression of stem cell markers SOX2, S100β, SOX9, KRT8/18, TACSTD2, and E-CAD), all as found in the tumor samples." (PMID 37614709, 2023). "CTH KO mice with GBM have significantly lower tumor volume, tumoral SOX2 expression and no alteration in the levels of tumoral vascular density compared to WT mice with GBM." (PMID 37300955, 2023). "We also tested the expression of SOX2, Nanog, and CD44 in three tumor model groups." (PMID 38008751, 2023). "In addition, RT-qPCR and Western blot experiments were employed to investigate the tumor stem cell markers OCT4 and SOX2 expression levels in GCSCs." (PMID 37980488, 2023). "Further immunohistochemical staining did not yield a clear classification of the tumors regarding either neural or astroglial origin: The early tumor cells (P21 mice) were positive for oligodendrocyte lineage marker OLIG2 and SOX2, a marker for CNS progenitor cells, e.g. NSCs." (PMID 37407554, 2023). "In UC, the expression of SOX2 varies according to the grade and stage of the disease with higher expression in high-grade NMIUC and MIUC compared to low-grade NMIUC and it is proposed that it plays a role in tumor maintenance and progression of the disease." (PMID 37298099, 2023).
tumor (continued). "Our findings therefore suggest that the absence of CTH in the tumor microenvironment and not in the tumor per se, is sufficient for regulating tumoral SOX2 expression." (PMID 37300955, 2023). "However, the expression of tumor stemness markers, including CD44, CD133, Nanog, Oct4, and SOX2, was similar between OECM1 EV and OECM1 RAD51 OE cells." (PMID 37798649, 2023). "PS of (P)RR and SOX2 expression increased with tumor malignancy irrespective of isocitrate dehydrogenase (IDH)1R132H or 1p19q status." (PMID 36646875, 2023). "This imaging revealed that most of the primary tumor cells that were SOX2-positive had very low levels of macroH2A2, whereas macroH2A2 signals was strongest in the adjacent SOX2-negative cells." (PMID 37244935, 2023). "Downregulating ACSVL3 decreased the expression of markers and regulators associated with stem cell self‐renewal, including CD133, Musashi‐1, SOX2, and aldehyde dehydrogenase, suggesting that ACSVL3 participates in the maintenance of GSCs and affects the tumor‐initiating capacity of GSCs." (PMID 37576862, 2023). "Importantly, tumoral c-Jun expression was positively correlated with SOX9, SOX2, OCT4, FTH1, FTL and TFRC expression in consecutive PDAC tumour tissues." (PMID 37143164, 2023). "Expectedly, only MOC2 eGFP+ cells also co- expressed SOX2 while no SOX2 expression was found in eGFP- tumor cells." (PMID 36735677, 2023). "Notably, high levels of SOX2, BMI1, and CXCR4, as well as low levels of UBE2C in the tumor core (T) significantly correlate with a greater tumor size and lymph node compromise." (PMID 38096163, 2023). "Notably, IL20RB overexpression upregulated the mRNA levels of several tumor stemness markers, including NANOG, SOX2 and POU5F1, while IL20RB knockdown downregulated their mRNA levels." (PMID 38098005, 2023). "High expression of SOX-2, NANOG, and OCT4 has been demonstrated in AME, suggesting that these proteins may act together to maintain undifferentiated stem cells in this tumour." (PMID 37559082, 2023). "Whether KLF4 can signal between tumor cells via exosomes remains a mystery, although exosomes are found to contain pluripotency genes (OCT4, SOX2, KLF4, C-Myc and Nanog) during embryonic development." (PMID 37031197, 2023). "The tumor stem cell markers CD133 and SOX2 were reduced by MMF intervention." (PMID 36711025, 2023). "In addition, our data revealed that SOX2 and BMI1 expression levels in tumor samples were also higher than those in normal tissues." (PMID 36411870, 2022). "This review article describes links between immunotherapies and microbiota in tumor-initiating stem-like cells (TICs), which have stem cell characteristics with self-renewal ability and express pluripotency transcription factors such as NANOG, SOX2, and OCT4." (PMID 35625986, 2022). "However, those patients in which the tumor had high SOX2 expression and MGMT was methylated showed a longer survival than when unmethylated with high SOX2 expression, or patients with low expression of SOX2 regardless of MGMT methylation status." (PMID 36333778, 2022). "The result suggests that histone methylation is altered by the newly identified extracellular tumor suppressors, which were enriched in CM by the overexpression of Oct4 and c-Myc and not by the overexpression of Sox2 and Klf4." (PMID 35547745, 2022). "Interestingly, squamous cell markers such as SALL4, NANOG, SOX2, BMI1, OCT3/4, HIWI, ABCG2, CD133, podoplanin, and ALDH1 also correlate with ESCC tumor stages, therapeutic resistance, relapse, and patient prognosis." (PMID 36474162, 2022). "However, inhibition of miR-21 significantly reduces the polarization of M2 GAMs and decreases levels of VEGF, TGF-β1, and IL-6 by decreasing activities of Sox2, PDCD4, and STAT3, ultimately inhibiting GBM tumor cell growth." (PMID 35572545, 2022).